IRS1 (insulin receptor substrate 1)
Diseases named in the same sentence as IRS1 in open-access papers (continued):
Sharing a sentence is not in itself a finding about the gene and the disease.
Insulin resistance (continued). "Reduced IRS-1 and GLUT4 expressions will contribute towards lower insulin-induced glucose transport, and these could explain the link between vitamin D deficiency, high serum PTH levels, and insulin resistance." (PMID 35859985, 2022). "Indeed, markers of insulin resistance, such as increased quantities of Ser-phosphorylated and inhibited IRS-1 downstream of the IR, have been identified in the hippocampus and cortex of AD patients, correlating with plaque deposition, disease progression and memory decline." (PMID 36117625, 2022). "By inhibiting the expression of the insulin receptor, insulin receptor substrate-1, and glucose transporter type 4 in 3T3-L1 adipocytes, IL-6 suppresses insulin activity A correlation has been shown between increased IL-6 levels and the occurrence of insulin resistance." (PMID 36248900, 2022). "However, whether IRS-1 phosphorylation is the only target of JNK-mediated insulin resistance remains to be further studied." (PMID 35509833, 2022). "Thus, PPARγ and IRS1 are related to insulin resistance and type 2 diabetes mellitus." (PMID 36292779, 2022). "Consequently, HM-chromanone may improve insulin resistance by downregulating the phosphorylation of IRS-1 serine through inhibition of negative regulators of insulin signaling and inflammation-activated protein kinases in L6 skeletal muscle cells." (PMID 36145191, 2022). "Importantly, GCs have been shown to directly induce insulin resistance in skeletal muscle by modulating the expression of IRS1 and PI3K in a similar manner to that reported here in WT mice with age – further supporting the premise that these age-dependent molecular changes are GC dependent." (PMID 36205523, 2022). "Furthermore, activation of this pathway was found to reduce expression of insulin receptor substrate-1 (IRS1) and PPARγ in mature human adipocytes and in hypertrophic adipocytes from ob/ob mice, thus contributing to adipocyte dysfunction and insulin resistance." (PMID 35769086, 2022). "It has been reported that TNF-α is the key mediator of insulin resistance because it can reduce insulin signaling by potently inhibiting insulin receptor (IR) tyrosine kinase, which might reduce the ability of IRS-1 to transduce signals in the insulin signaling system." (PMID 35320949, 2022). "Therefore, our study aimed to investigate whether MLE or 1-DNJ supplementation could improve muscle insulin resistance by activating the IRS-1/PI3K/Akt pathway in the skeletal muscles of diabetic db/db mice." (PMID 36295064, 2022). "Thus, TFs could promote glucose homeostasis and prevent the development of insulin resistance by regulating the IRS-1/Akt/GLUT4 signaling pathway." (PMID 35886943, 2022). "However, the S307 phosphorylation of IRS-1, a hallmark of insulin resistance, was also decreased by the TCDD rather than increased in unstimulated cells." (PMID 36358481, 2022). "In the same way, pro-inflammatory cytokines participate in insulin resistance in the adipose tissue via the activation of IκB kinase and c-Jun N-terminal kinase, responsible for dephosphorylating the serine of the insulin receptor substrate-1 (IRS-1), turning insulin into less efficient." (PMID 34829598, 2021). "Interestingly, miR-96 was upregulated in the liver cells with palmitate exposure or with HFD exposure, targets IRS1 and insulin receptor and may contribute to fatty acid induced hepatic insulin resistance." (PMID 34831343, 2021). "Considering that insulin resistance is an underlying pathology of several neurodegenerative diseases, it is plausible that excess BCAAs persistently overstimulate mTORC1, resulting in the p70S6K1-mediated negative feedback on IRS-1." (PMID 34215308, 2021).
Insulin resistance (continued). "NO donor agents and the NO generated by iNOS persuaded insulin resistance via the S-nitrosation of proteins entailed in the primary stages of insulin action, for instance, insulin receptor β (IRβ), insulin receptor substrate 1 (IRS-1), and protein kinase B (Akt)." (PMID 34361685, 2021). "It has been defined that brain insulin resistance occurs primarily with early hyperactivation of insulin signaling, including mTOR hyperactivity, which causes negative feedback on the insulin receptor, IRS1 and mTOR itself." (PMID 34065168, 2021). "In addition, HCV infection leads to a defect in insulin receptor substrate (IRS)-1 association with the IR and insulin signaling defects in hepatic IRS-1 tyrosine phosphorylation and phosphatidylinositol 3-kinase (PI3-kinase) association/activation, which contribute to insulin resistance." (PMID 34670509, 2021). "Thus, NAG-1 may improve glucose metabolism and attenuate insulin resistance via the activation of the IRS1/AKT/PI3K signaling pathway." (PMID 34294853, 2021). "Given that diabetes-induced brain insulin resistance is associated with the elevated glucocorticoid level caused by alteration of HPA axis, the effects of ZJJ on diabetes-related depression may be related with the hippocampal IR/IRS-1 signaling." (PMID 34149862, 2021). "In addition, rh-aFGF135 may improve insulin resistance partly by increasing the protein expression of p-IRS-1 (human Ser 307)." (PMID 33681196, 2021). "It was reported that PYCR1 silencing could inhibit the expression of insulin receptor substrate 1 (IRS1) and insulin resistance via the suppression of the c‐Jun N‐terminal kinase (JNK) signaling pathway, which subsequently inhibited HCC cell proliferation and promoted cell apoptosis." (PMID 34239351, 2021). "For example, TNF-activated signaling molecules such as IKK, JNK, S6 kinase, and mammalian target of rapamycin (mTOR) could potentially phosphorylate insulin receptor substrate 1 (IRS1) to attenuate insulin signaling and subsequently contribute to the development of insulin resistance." (PMID 33150865, 2020). "Moreover, NGF could reduce insulin resistance both in vitro and in vivo by activating insulin receptor substrate 1 (IRS1)." (PMID 33292292, 2020). "However, there was a negative correlation between increased species diversity and IRS-1 protein levels, suggesting that microbiome changes may be aiding in the observed insulin resistance (r= −0.6)." (PMID 32927823, 2020). "For instance, common variants in the gene encoding insulin receptor substrate 1 (IRS1), an important component of the intracellular signalling pathway, are associated with T2D, most likely by making affected individuals more susceptible to developing obesity-associated insulin resistance." (PMID 33233816, 2020). "To determine whether overexpression of Nanog prevents Aβ-impaired neuronal insulin signaling, we performed western blotting to detect the level of insulin receptor substrate 1 (IRS-1) phosphorylation at Ser307, a typical marker linked to the severity of insulin resistance." (PMID 32471175, 2020). "Moreover JNK was proposed to induce insulin resistance in obesity via four different mechanisms, including direct inhibition of IRS1 phosphorylation, induction of metabolic inflammation, increased adipogenesis and metabolic efficiency, and negative regulation of the PPARα‐FGF21 axis." (PMID 33038072, 2020). "Additionally, in p70 S6K-deficient mice, the ser307 and ser636/639 phosphorylation of IRS-1, induced by a high fat diet, was noticeably reduced, indicating that p70 6SK might be involved in the induction of insulin resistance." (PMID 32664532, 2020). "Furthermore, administration with trilobatin for 4 weeks significantly improved insulin resistance by decreasing fasting blood glucose and insulin in serum, enhancing the phosphorylation of IRS1 and AKT, and recovering the expression and translocation of GLUT4 in ob/ob mice." (PMID 33062046, 2020).
Insulin resistance (continued). "As a bridge between AD and type 2 diabetes, activation of c-Jun N-terminal kinase (JNK) pathway with the ensued serine phosphorylation of the insulin response substrate (IRS)-1/2 may be at the crossroads of insulin resistance and its subsequent dysmetabolic consequences." (PMID 33224105, 2020). "ZBPYR may correct CNS insulin resistance by regulating p-IRS1 and p-AKT." (PMID 32372981, 2020). "Hyperinsulinemia as a compensation for insulin resistance activates insulin receptor substrate-1, together with the downstream mitogen-activated protein kinase and phosphatidylinositol-3 kinase/Akt pathway, which could subsequently activate peroxisome proliferator activated receptor γ." (PMID 31200528, 2019). "Moreover, in HFD-fed mice, the insulin resistance in adipose tissues could be mitigated by treatment with dioscin through insulin receptor substrate 1 (IRS-1)/PI3K/Akt pathway." (PMID 31511824, 2019). "In addition, quantification of a number of well-characterized hepatic insulin signaling genes (Irs1, P85a, and P110b) that have been recognized to correlate with insulin resistance indicated that loss of Agrp did not prevent the changes in these genes." (PMID 30794724, 2019). "However, the present work is the first to examine and verify the defects in insulin signaling in the hippocampi of AlCl3-treated rats to demonstrate that insulin resistance and wrecked insulin signaling have started when AlCl3 insult promoted IRS1 serine phosphorylation." (PMID 31137621, 2019). "Interestingly, our data indicate that NGF may counteract the detrimental effects of brain insulin resistance by acting on the IRS1 stimulation, the early, main and common effector of insulin and IGF1 receptors signalings." (PMID 29736736, 2019). "Moreover, TNF-α could induce serine phosphorylation of IRS-1 and inhibit its triggering of downstream signals, leading to insulin resistance." (PMID 31440472, 2019). "Additionally, HUVECs exhibited ER stress and insulin resistance when incubated with tunicamycin; however, co-incubation with ucOC (5 ng/mL) for 4 h reduced the ER stress and increased the phosphorylation of insulin receptor substrate 1 (IRS-1), a molecule involved in insulin signal transduction." (PMID 30287742, 2018). "In addition, in vivo and in vitro experiments show that Aβ induces serine phosphorylation of insulin receptor substrate 1 (IRS-1) instead of tyrosine phosphorylation; this switch has been described as a major mechanism that triggers peripheral insulin resistance." (PMID 29743868, 2018). "Hence, we concluded that miR-222 could involve hepatic insulin resistance at least in part through IRS-1 repression." (PMID 29364977, 2018). "Insulin signaling pathway results in phosphorylation of the insulin receptor-interacting protein (IRS-1), particularly, a decrease in IRS-1 phosphorylation may induce insulin resistance, while an increased phosphorylation on serine 312 of IRS-1 has opposite effects." (PMID 29949869, 2018). "PTP1B can directly interact with the insulin receptor and insulin receptor substrate 1 (IRS-1), dephosphorylating the tyrosine residues in the activation loops of these molecules to down-regulate insulin signaling, thereby contributing to an insulin resistance phenotype in T2DM patients." (PMID 29257069, 2017). "Thus, the main causes of insulin resistance are thought to include significant decreases in IRS-1 protein levels, insulin-stimulated IRS-1 tyrosine phosphorylation, and IRS-1-associated PI3K activity observed in subjects with insulin resistance and type 2 diabetes." (PMID 29259227, 2017). "To test brain insulin resistance, we measured cortical levels of glucose and insulin and analyzed the expression and activation of the insulin receptor (IR) and its downstream signaling molecules IR scaffold-1 (IRS1), protein kinase B (AKT) and mammalian target of rapamycin (mTOR)." (PMID 26858121, 2016).
Insulin resistance (continued). "Thus, it was proposed that therapeutic interventions to mediate the IRS-1 protein level might be a novel approach for the treatment of insulin resistance." (PMID 27689988, 2016). "It is known that activation of the renin-angiotensin system may lead to insulin resistance in the vasculature; Ang-II impairs insulin receptor intracellular signaling, inhibiting insulin receptor substrate-1 (IRS-1) phosphorylation and phosphatidylinositol (PI) 3–kinase activation." (PMID 26779026, 2015). "Activated AMPK could abolish inflammation through the MAPKs signaling pathway; activated AMPK could attenuate insulin resistance by phosphorylating IRS-1, AKT and dephosphorylate ERK, JNK and NF-κB; it also suppresses fatty acid synthesis, gluconeogenesis and increases mitochondrial β-oxidation." (PMID 26705405, 2015). "Therefore, keeping the normal phosphorylation of IRS-1 may be key to inhibit insulin resistance and improve insulin signaling." (PMID 25912041, 2015). "In logistic regression models adjusted for each other, or containing age and sex, with and without further adjustment for markers of insulin resistance/sensitivity, neither the IRS1 allele A, nor the PPARG was significantly associated with prevalent type 2 diabetes." (PMID 24447396, 2014). "Likewise, the ubiquitin-mediated degradation of IRS-1/2 also promotes insulin resistance." (PMID 25346723, 2014). "Other studies at the IR itself suggest that insulin resistance may involve alterations in IR serine phosphorylation or in tyrosine phosphatase activities, possibly at Y972, whose phosphorylation is critical for interaction with IRS-1." (PMID 25259572, 2014). "We observed that neither IRS1 972Arg allele nor PPARG 12Ala were associated with type 2 diabetes or insulin resistance/sensitivity, but in a model containing both the alleles and their interaction term, the presence of the PPARG Pro12 conferred a 64% risk of prevalent type 2 diabetes." (PMID 24447396, 2014). "However, phosphorylation of IRS-1 at Ser 307 also inhibits the interaction between the phosphotyrosine binding domain of IRS-1 with the phosphorylated NPEY motif in the activated IR, disrupting insulin signaling, and may ultimately cause insulin resistance." (PMID 24918297, 2014). "However, evodiamine inhibited insulin-stimulated phosphorylation of mTOR and S6K, leading to suppression of IRS1 serine phosphorylation in adipocytes, suggesting evodiamine acts to improve insulin resistance by repressing activation of mTOR-S6K signaling by insulin." (PMID 24391749, 2013). "Moreover, TNF-alpha also has a role in the development of insulin resistance; in fact, it affects insulin sensitivity by changing the phosphorylation of insulin receptor substrate-1 and interferes with the insulin signaling cascade, thereby leading to insulin resistance." (PMID 24259948, 2013). "Another study has shown that the mechanism by which FFA induces insulin resistance involves the intramyocellular and intrahepatocellular accumulation of triglycerides and diacylglycerol, which then reduce tyrosine phosphorylation of insulin receptor substrate-1 (IRS-1) and IRS-2." (PMID 23983807, 2013). "Furthermore, CYP2J3 overexpression significantly improved insulin resistance, at least in part through eNOS, IRS-1, and PI3K/AKT signaling pathways, as well as adenosine monophosphate-activated protein kinase (AMPK) signaling pathways in liver, muscle, heart, and kidney." (PMID 22189162, 2011). "A low adipocyte IRS-1 expression may thereby be a marker for insulin resistance." (PMID 20634940, 2010). "Furthermore, in vitro studies revealed that treatment with chemerin induces insulin resistance in human skeletal muscle cells at the levels of IRS1 (Insulin receptor substrate 1), protein kinases B (PKB), and Glycogen synthase kinase 3 (GSK3) phosphorrylation and glucose uptake." (PMID 22375203, 2010). "The possible molecular mechanism of TNF-α-induced insulin resistance may involve IRS-1." (PMID 18604303, 2008).
Insulin resistance (continued). "This increases the phosphorylation of IRS1, PI3K, AKT, and GSK3β, while decreasing the phosphorylation of GS, thereby enhancing the transmission of insulin resistance signaling pathways in liver cells." (PMID 41497732, 2026). "It has been shown that there is an increased SOCS-1 expression in insulin-sensitive tissues in obesity and that this inhibits the phosphorylation of IRS-1 and IRS-2, leading to the inhibition of downstream signaling and insulin resistance." (PMID 40572705, 2025). "miR-let-7b-5p is also enriched in pancreatic cancer cell-derived EVs and can promote lipid accumulation, upregulate FOXO and STAT3, and downregulate IRS1 and GLUT4 in C2C12 skeletal muscle cells, indicating a role in the development of insulin resistance." (PMID 41347018, 2025). "In IRS1- or IRS2-knockout mice, the peripheral tissues of the mice exhibit insulin resistance due to the blockage of PI3K/AKT signaling, and the impairment of insulin secretion further contributes to the development of diabetes mellitus." (PMID 40747301, 2025). "TNF-α levels are inversely correlated with insulin sensitivity, while IL-6 and IL-1β inhibit insulin receptor substrate 1 (IRS-1); moreover, elevated levels of leptin in women with pregestational obesity contribute to insulin resistance." (PMID 41374008, 2025). "The SARS-CoV-2 RNA fragment activates protein kinase R (PKR), which phosphorylates insulin receptor substrate 1 (IRS-1) serine, resulting in insulin resistance." (PMID 40469441, 2025). "The findings demonstrated that DP increased glucose uptake by potentially modulating the IRS1/GLUT4 signaling pathway, thus alleviating insulin resistance in HepG2 cells." (PMID 40565724, 2025). "Persistently high levels of IL-1α and IL-1β impair insulin signaling by reducing insulin receptor substrate 1 (IRS-1) phosphorylation and disrupting its downstream pathways, leading to insulin resistance." (PMID 41087719, 2025). "On one hand, PGE2 binds to the EP3 receptor to activate extracellular signal-regulated kinase 1/2 (ERK1/2), thereby inducing serine phosphorylation of insulin receptor substrate 1 (IRS1) and ultimately exacerbating insulin resistance." (PMID 41140404, 2025). "Human insulin can activate IRS-1 phosphorylation on Ser-307 and mice fed on a high-fat diet; an IRS-1 Ser307Ala mutant exhibited more severe insulin resistance than controls, demonstrating that Ser-307 is essential for insulin signaling." (PMID 40141412, 2025). "In PCOS, PTM-mediated signaling perturbations are central to drive key pathological features, such as insulin resistance; hyperphosphorylation of IRS-1 impairs PI3K/Akt signaling, inducing GC insulin resistance." (PMID 40862771, 2025). "Additionally, the HCV core protein has been associated with disturbances in glucose and lipid metabolism, promoting insulin resistance through interference with IRS-1/PI3K signaling pathways, which may indirectly contribute to cognitive decline and affective disorders." (PMID 40868568, 2025). "Concurrently, levels of insulin receptor β subunit, IRS1 and Akt substrate of 160 kDa (AS160) were all decreased, pointing to hepatic insulin resistance." (PMID 40013621, 2025). "Mechanistically, TMAO disrupts insulin signaling by activating inflammatory pathways, such as the NLRP3 inflammasome, which impairs insulin receptor substrate-1 (IRS-1)-mediated signaling, leading to insulin resistance and glucose intolerance." (PMID 40077680, 2025). "Metformin reverses brain insulin resistance by promoting AKT and IRS1 phosphorylation, though one study did not observe these effects." (PMID 41146261, 2025). "As shown in the insulin resistance pathway, expression of IL6 and IRS1 were upregulated, while INSR was downregulated in T2DM macaques." (PMID 40878918, 2025). "For instance, exosomes from the muscle and fat cells contain miR-1 and miR-133, which target IRS-1 and INSR, inhibiting insulin signaling and leading to insulin resistance." (PMID 41438998, 2025).